IL1B (interleukin 1 beta)
Diseases named in the same sentence as IL1B in open-access papers (continued):
Sharing a sentence is not in itself a finding about the gene and the disease.
cancer (continued). "Moreover, TAT-FADD targets NF-κB signaling to suppress the expression of anti-apoptotic genes Bcl2, cIAPs, RIP1, and cFLIPL in cancer cells, and TAT-FADD abolishes NLRP3 inflammasome transcriptional priming and processing of IL-1β in colon carcinoma HCT116 cells." (PMID 32961826, 2020). "Similarly, treatment with MCC950 attenuated mechanical allodynia in a rodent model of cancer-induced bone pain, and in oxaliplatin-induced peripheral neuropathy model and restored the increased expression levels of NLRP3, ASC, caspase-1 and IL-1β in spinal cord to basal levels." (PMID 32973552, 2020). "While this study does not elucidate whether IL-18 or IL-1β induced production by anti-PD-L1 would be beneficial or detrimental for cancer treatment, it pinpoints an important discrepancy between anti-PD-1 and anti-PD-L1 mAbs." (PMID 33261061, 2020). "Furthermore, we characterized alterations in the gene expression profiles of the pro-inflammatory cytokines IL-8, IL-6, TNF-α and IL-1β in a cancer and a noncancer colon cell line, mimicking an inflamed intestinal epithelium by IL-1β stimulation." (PMID 32326355, 2020). "However, the repercussions on the course of cancer are complex, and both positive and negative functions of IL-1β have been described." (PMID 32635472, 2020). "Recent studies have also suggested a repressor function of TAZ in differentiation of cancer cells and in the negative regulation of peroxisome proliferator-activated receptor-γ in mesenchymal stem cell differentiation, and NFAT5 in response to hyperosmotic stress and IL1β in inflammation." (PMID 33023162, 2020). "In addition, IL1B-, PTCH- and PTCL-stimulation of MSC activate “pathways in cancer”." (PMID 31086407, 2019). "Since IL-1β is the major cytokine secreted upon NLRP3 inflammasome activation in macrophages, we investigated whether IL-1β would increase the metastatic potential of cancer cells." (PMID 31439870, 2019). "The administration of IL1B-, PTCH- and PTCL-primed MSC could therefore lead to negative effects in patients with a cancer predisposition." (PMID 31086407, 2019). "Indeed, Cxcl1 expression was downregulated by Kras or Chuk silencing and IL-1β induced Cxcl1 expression by two different cancer cell lines and Ppbp by LLC cells (MC38 cells do not express Ppbp25)." (PMID 29445180, 2018). "Moreover, Choi and colleagues reported that açaí treatment down-regulated myeloperoxidase (MPO) and proinflammatory cytokines (TNF-α, IL-1β and IL-6), inhibited cyclooxygenase 2 (COX-2), PCNA and Bcl-2, and increased Bad and cleaved caspase-3 expression in an experimental model of cancer colon." (PMID 29966007, 2018). "The increased concentrations in the TME of cytokines and growth factors such as CCL2, IL-1β, M-CSF, TGF-β, and VEGF, induced by cancer cells and the intervention of the immune system, promote the enlistment of CAFs and TAMs as contributors of nutrients and growth factors needed by cancer cells." (PMID 30627563, 2018). "Furthermore, the oncogenic dysregulation of the RAS, MYC and the MAPK pathways in cancer cells are known to induce the production of growth factors and cytokines such as VEGF, IL-6, IL-10, and IL-1β, leading to the recruitment and the tumorigenic transformation of macrophages." (PMID 28969664, 2017). "Thus, targeting glucose/NEDD4-dependent H3 ubiquitination and subsequent transcription of IL1α/IL1β and GCLM may be an effective way to target cancers." (PMID 28300060, 2017). "Hence, targeting this newly identified signaling pathway, such as NEDD4, Gcn5 or their transcriptional targets including IL1α, IL1β and GCLM may be promising approaches for cancer therapy." (PMID 28300060, 2017). "The negative correlation also found between the plasma concentrations of IL-1β and numbers of CD4+NKG2D+ T cells in cancer patients may simply be an independent variable resulting from the fact that IL-1β is typically activated in situations where TNF-α is produced." (PMID 26486970, 2015).
cancer (continued). "We continued to examine whether the Chinese medicine XAT might affect the activity of the proinflammatory cytokines IL-1β and TNF-α, which are important in the development of inflammation and cancer pain, as well as the anti-inflammatory cytokine IL-10, which may inhibit inflammation and pain." (PMID 26617438, 2015). "Indeed, while PC-3 cells express Il1b, the transcript was undetectable in SKOV3 cells, suggesting a mechanism to explain the differential stimulation of C/EBPβ expression in myoblasts by these two cancer cell lines." (PMID 26709824, 2015). "In fact, neither neutralization of the low amounts of IL-1β produced after PolyIC-treatment of the cancer cells nor caspase-1 or pan-caspase inhibitors, both of which have the potential to interfere with IL-1β processing and activation, significantly inhibited DC activation." (PMID 25888634, 2015). "It is interesting that we did not observe phosphorylation of S102 in IL-1β treated cells by either mass spectrometry or western analysis, suggesting that different cytokines could lead to differential phosphorylation in cancer cells." (PMID 26318844, 2015). "Likewise, OC patients with a confirmed FH of cancer had urinary IL-1β levels several fold higher than OC patients without a known FH of cancer." (PMID 26357657, 2015). "In GBM cells, ICAM-1 expression has been shown to increase following stimulation with proinflammatory cytokines, such as interleukin-1β (IL-1β), tumor necrosis factor-alpha (TNFα), and interferon-gamma (IFN-γ), indicating that ICAM-1 is one of the inflammatory mediators also in this type of cancer." (PMID 26798546, 2015). "Compared to DVT- cancer patients, DVT+ showed an increased fold change of 1.28 (95% CI: 1.20–1.37; p<0.0001), 1.34 (95% CI: 1.23–1.46; p<0.0001), 1.41 (95% CI: 1.30–1.54; p<0.0001), and 1.61 (95% CI: 1.45–1.78; p<0.0001) for IL-6, TNF-α, Il-1β, and VEGF, respectively." (PMID 26192925, 2015). "Using the age matched cohort subset, urinary IL-1β levels were analyzed with respect to a family history of cancer though the BRCA1 status of these patients could not be confirmed." (PMID 25403235, 2014). "Human monocytic THP-1 cells overexpressing a mutant variant of NLRP3 bearing the Q705K SNP have been reported to greatly respond to the inflammasome agonist alum and to trigger the production of IL-1β and IL-18, implying that overt NLRP3 activation could be detrimental for certain types of cancer." (PMID 25071785, 2014). "While the number of specimens was small, in a patient with benign ovarian disease and no known family history of cancer, urinary IL-1β levels were 0.33 pg/ml; while average levels were 0.96 pg/ml in five patients with benign ovarian disease and a family history of cancer." (PMID 25403235, 2014). "However, neither IL-1α nor IL-1β was detected in the supernatants of gastric fibroblasts under normal conditions or when incubated with cancer cell–conditioned media." (PMID 23593346, 2013). "Here, we investigated the mechanism of analgesic action of Z-360 in a severe cancer-induced pain model in mice, which is considered to be opioid-resistant, by examining ephrin B1 gene expression, N-methyl-D-aspartate receptor NR2B subunit phosphorylation, and interleukin-1β (IL-1β) production." (PMID 20979661, 2010). "In summary, we have identified a novel pain cascade, IL-1β (cancer-inoculated region) → ephrin B1 (DRGs) → NR2B (spinal cord) → pain, that may be responsible for the development of opioid-resistant pain in the mouse model of cancer-induced pain." (PMID 20979661, 2010). "These include interleukin-1 beta (IL-1b) in activated monocytes, Tumour Necrosis Factor-alpha (TNF-α), Plasminogen Activator Inhibitor Type 1 (PAI-1) and adrenomedullin all of which have been shown to have active participation in various aspects of cancer development." (PMID 15813980, 2004).
cancer (continued). "Notwithstanding cancers with other mutations and other myeloid cells like neutrophils and mast cells that might also fuel tumors with IL-1β, we define here a non-oncogene addiction of KRAS and IL-1β, in tandem with their partners in crime VCAN and IKKβ." (PMID 36980752, 2023). "In this setting, cancer-derived exosomes may trigger distinct intracellular signaling pathways in receptor cells, culminating in NF-κB activation and the subsequent expression of the IL-1β gene or the activation of inflammasomes through NLRP3 for the cleavage of pro-IL-1β into its active form." (PMID 36072935, 2022). "This raises the question of whether or not to use IL-1β inhibitors in cancer treatment." (PMID 32635472, 2020). "And this study provided evidence that high NLRP3 inflammasome (NLRP3/IL-18/IL-1β/ASC) expression in LSCC cancer tissues suggests a poor prognosis of LSCC without distant metastasis in a Chinese population, which may help identify a new prognosis factor for LSCC." (PMID 31312615, 2019). "Indeed, KRAS-mutant cancer cells displayed non-canonical endogenous NF-κΒ activity evident by enhanced nuclear localization and/or DNA-binding activity of RelB, ΙκΒβ, and ΙΚΚα, which was further inducible by exogenous IL-1β." (PMID 29445180, 2018). "However, the upregulation of IL-1β in the cancer group was not inhibited by BE." (PMID 26649065, 2015). "Intracellular LPS-induced significant LDH release and increased secretion of IL-18 and IL-1β in IHGK and cancer cells, but not in normal HOKs, indicating selective cytotoxicity and pyroptosis." (PMID 40338411, 2025). "Three pro-inflammatory cytokines (IL-1β, IL-1α, TARC for adolescents with cancer and IL-1β, I-309, oncostatin-M for adolescents without cancer) demonstrated significantly higher levels in FF of adolescents compared to oocyte donors." (PMID 39211054, 2024). "In the present study, we found that the mtDNA-STING pathway was important for the protective antitumor effect of an irradiated cancer cell vaccine, while TLR9 and IL-1β signaling was not." (PMID 32398808, 2021). "These correlations were independent of human HCC stage, suggesting that the downregulation of SPTBN1 and the upregulation of IL-1α, IL-1β and IL-6 occur in HCC throughout all stages of cancer progression, and also irrespective of human hepatitis virus status." (PMID 33754058, 2021). "Unlike cancer cells, the co-treatment of macrophages with ME and high FRH (41 °C) induced a strong up-regulation of IL-1β and IL-6 mRNA expression." (PMID 34201348, 2021). "Therefore, inhibition of IL-1β may help in the reactivation of specific antitumor immunity and in a therapeutic M2 to M1 macrophage switch, while administration of COX-2 inhibitors (e.g., aspirin) may aid in overcoming the mechanisms of cancer immunosuppression." (PMID 33171792, 2020). "Interestingly, SAHA promoted IL-1β production in murine bone marrow derived macrophages and human dendritic cells stimulated with LPS, suggesting SAHA may have wider applications as a modulator of macrophage function in other settings of infectious disease and cancer." (PMID 32793237, 2020). "Under pro-inflammatory conditions (IL-1β treatment), the impact on cytokine mRNA levels of NF-κB downstream genes was studied in human colon cell lines, comparing noncancer (HCEC-1CT) and cancer cells (HT-29)." (PMID 32326355, 2020). "Previous studies have demonstrated that PDGFA contributes to cancer stemness, but the molecular mechanisms driving PDGFA expression in GSCs under IL-1β treatment are still not elucidated." (PMID 31300060, 2019). "No significant changes in the level of IL-1B, TNF-α, and TGF-β1 were observed in co-culture with cancer cells in comparison to monoculture." (PMID 30310111, 2018). "Via ELISA assay, higher level of IL-1β was detected in the 231-MSC coculture, as well as in IGROV1-MSC coculture, which was derived from UC-MSCs rather than cancer cells." (PMID 29670904, 2018).
cancer (continued). "In this study, higher serum levels of IL-1β, IL-6, IL-8, and TNF-α were observed in cancer patients of the locally advanced group than those of the normal and resected groups." (PMID 30513776, 2018). "We observed sustained IL-1β expression by THP-1, but not NPC cells, suggesting that different types of cancer cells have different ability to produce this factor." (PMID 27487154, 2016). "Alleviation of cancer-related symptoms by MR16-1 treatment seems to contribute to the reduction of TNF-α and IL-1β levels rather than the MR16-1 treatment having a direct impact on their levels by the blockade of IL-6 signaling." (PMID 27068103, 2016). "Studies have identified IL-12, IL-23, IL-1β, and TGF-β as regulators of Th17/Th1 cell conversion in several immunological contexts but not in cancer." (PMID 26583099, 2015). "We observed that hMSCs formed niche-like structures when co-cultured with cancer cells expressing high levels of CDH1 and lacked IL-1β." (PMID 26204886, 2015). "IL-1β did not regulate CCR6 or CCR7, two other CC chemokine receptors related to cancer metastasis, in either Tca8113 or Hep2 cells." (PMID 26176534, 2015). "The present data showed that, as opposed to in chondrocyte or cancer cells, the mRNA and protein expression of autophagy-related genes, LC3 and Beclin-1, showed no change in response to TNF-α and IL-1β." (PMID 26165348, 2015). "Spontaneous production of cytokines, such as IL-6, TNF-α, Il-1β and VEGF were significantly higher in both groups of cancer patients with and without DVT than those from healthy controls (p<0.0001)." (PMID 26192925, 2015). "Compared to control group, higher plasma levels of CRP, fibrinogen, IL-6, TNF-α, IL-1β, MMP-9, VEGF, TF antigen, and sP-selectin were observed in cancer patients with and without DVT (P<0.01)." (PMID 26192925, 2015). "Though we could not identify the lack of family history of cancer in most of the OC patients, in those OC patients with confirmed family history of cancer, average urinary IL-1β levels were 6.33 pg/ml, while the average urinary IL-1β levels of the remaining OC patients was 1.16 pg/ml." (PMID 25403235, 2014). "However, how IL-1β may contribute to the development of cancer has not been fully explored." (PMID 23174018, 2012). "TNF-α has been shown to upregulate MMP-9 gene expression in malignant carcinoma via TNF-R1, and TNF-R1 but not TNF-R2 has been shown to be important in inflammatory responses involving IL-1β and MMP-3 and -9 in murine brain injury." (PMID 19435506, 2009). "Interestingly, we found that in the absence of cancer cells, although BCG or VPM vaccines induced an inflammatory cytokine response (induction of tnfa, il1b and il6), this was not translated into a marked innate cellular response." (PMID 39114912, 2024). "Importantly, we showed that ectopic expression of PLK2 in several types of cancer cells promoted processing of Caspase-3, cleavage of GSDME, DAMPs release, and cell death, but not IL-1β secretion." (PMID 36646704, 2023). "To further investigate the connection between STAT1, STAT3 and said cytokines in drug resistance, we have treated cells (EP and LP) with cytokine-neutralized (IL-6, IL-10 and IL-1β) MDSC supernatant (in presence or absence of these cytokines), keeping untreated cancer cells as a control." (PMID 38304256, 2023). "ATP is another molecule released by cancer cells after ICD, which functions as a find-me signal, but also binds to ionotropic P2X purino-receptor 7 (P2RX7), inducing inflammasome activation and IL1β release." (PMID 36497148, 2022). "Identification of the IL-1β/Glo1/MG-H1/TGF-β1/FAK axis in ATC cell aggressiveness suggests that IL-1β and Glo1, which orchestrate the mechanism, may represent novel potential therapeutic targets for ATC, which remains one of the most lethal human cancers." (PMID 31174324, 2019).
cancer (continued). "Moreover, whereas we identified the effects of the overall inflammatory mediators on cancer incidence through DII, we did not observe the effects of individual inflammatory markers such as hs-CRP, IL-1β, IL-4, IL-6, IL-10 or (TNF)-α." (PMID 31652856, 2019). "This study included both pro‐inflammatory (IL‐1B, IL‐6, IL‐8, IL‐12 (p40, p70), TNF‐α, and IFN‐γ), and anti‐inflammatory (IL‐4, IL‐6, IL‐10, TGF‐β), peripheral cytokine blood serum markers with no significant findings evident between cancer survivors and matched controls." (PMID 37751068, 2023). "Interestingly, we confirmed that P2X7 activation in TAMR-MCF-7 cells did not activate the classically known inflammasome pathways (IL-1β and IL-18), showing that P2X7 may control a non-canonical pathway in cancer cells." (PMID 31406126, 2019).